U8 (U8 small nucleolar RNA )
Synonyms: LOC124900305
Gene: Small nucleolar RNA gene on chromosome 11 (123,301,390 to 123,301,523, forward strand). Ensembl gene ENSG00000200496.
Gene Ontology:
Biological process: RNA processing
Cellular component: nucleolus
Homologues: Orthologues: chimpanzee U8 (99% identical), macaque U8 (95% identical), rabbit U8 (59% identical), mouse Gm56239 (55% identical). Paralogues in human: U8 (87% identical), U8 (85% identical), U8 (84% identical), U8 (82% identical), U8 (81% identical), U8 (80% identical), U8 (79% identical), U8 (78% identical), U8 (77% identical), U8 (76% identical), U8 (71% identical), U8 (66% identical), and 2 more.